INS (insulin)
Diseases named in the same sentence as INS in open-access papers (continued):
Sharing a sentence is not in itself a finding about the gene and the disease.
Cerebral ischemia (continued). "Both insulin and α-T administration significantly increased the activity of Na+,K+-ATPase in the brain cortex of rats with brain ischemia and subsequent reperfusion, their effects were found to be additive." (PMID 34769198, 2021). "The impaired insulin action in the gastrocnemius muscles was highlighted by the reduction of Akt phosphorylation after cerebral ischemia." (PMID 32492962, 2020). "Another study reported that, in diabetic rats subjected to cerebral ischemia and reperfusion, insulin treatment decreased brain lesion volume, as well as basal and injury-induced apoptotis." (PMID 27296974, 2016). "Reasons for dropping out were elevated triglyceride level (n=1), initiation of insulin treatment (n=2), cerebral ischemia (n=1), and dislike of the taste (n=1)." (PMID 27343205, 2016). "In the basic studies, insulin treatment protects neurological function following cerebral ischemia in hyperglycemic rats." (PMID 25223305, 2014). "The secondary aim is to explore the possible mechanisms (with specific focus on NO/superoxide/peroxynitrite) of insulin in amelioration of focal cerebral ischemia-reperfusion (FC I/R) injury in streptozotocin (STZ)-diabetic rats." (PMID 25223305, 2014). "We first investigated the effect of insulin treatment on release of Cytc from the mitochondria into the cytosol and subsequent cell death in a rat model of global brain ischemia/reperfusion injury." (PMID 24223835, 2013). "Our studies have identified insulin as a potent growth factor that induces cell survival signaling and prevents neuronal apoptosis following global brain ischemia." (PMID 24223835, 2013). "We next confirmed these results in rats by in vivo application of insulin in the absence or presence of global brain ischemia and determined that Cytc Tyr97-phosphorylation is strongly induced under both conditions but cannot be detected in untreated controls." (PMID 24223835, 2013). "But, in our experiments, there was no significant change in IRS-2 phosphorylation at Ser731 in the hippocampus or frontal cortex under the influence of intranasally administered insulin or inhibitors of autophagy and apoptosis in rats exposed to brain ischemia and reperfusion." (PMID 39057034, 2024). "It has been shown that insulin with various delivery methods (subcutaneous, intraperitoneal, intravenous, and intracerebroventricular) positively affects the survival and cognitive functions of animals that have undergone cerebral ischemia." (PMID 36834685, 2023). "The vasoactive effect of insulin is widely known, which, along with its neuroprotective effect, plays an important role in the implementation of the protective functions of insulin in cerebral ischemia." (PMID 36834685, 2023). "Despite a significant number of studies on the effects of peripheral and intracerebroventricular insulin administration to correct the consequences of cerebral ischemia, there are relatively few data on the use of INI, despite the promise of this method for correcting ischemic damage." (PMID 36834685, 2023). "Thus, α-T enhances the protective effects of insulin on cultured cortical neurons in oxidative stress and in the brain cortex of rats with cerebral ischemia/reperfusion injury." (PMID 34769198, 2021). "Therefore, cerebral ischemia has an adverse effect on the insulin signaling in the gastrocnemius muscles and liver involving oxidative stress and inflammation, with AG490 improving the impairment." (PMID 34943061, 2021). "Additionally, the impairment of insulin signaling in the gastrocnemius muscles was noted in rats with cerebral ischemia, with propranolol improving the impairment by reducing oxidative stress and tumor necrosis factor-α signaling." (PMID 32492962, 2020). "Additionally, the impairment of insulin signaling in the gastrocnemius muscles was noted in rats with cerebral ischemia, as well as its improvement due to the use of propranolol." (PMID 32492962, 2020).
Cerebral ischemia (continued). "However, some quantity of Y-27632 should have been absorbed from the pial surface to systemic circulation and induced glucose-stimulated insulin secretion at the global brain ischemia." (PMID 28270098, 2017). "Insulin was reported to confer a neuroprotective effect in cerebral ischemia in MCAO." (PMID 26863436, 2016). "This present study aims to explain the contradiction among nitric oxide (NO)/superoxide/peroxynitrite of insulin in amelioration of focal cerebral ischemia–reperfusion (FC I/R) injury in streptozotocin (STZ)-diabetic rats and to delineate the underlying mechanisms." (PMID 25223305, 2014). "Importantly, in vivo insulin treatment leads to strong induction of tyrosine phosphorylation (lane 3), and this effect is persistent after global brain ischemia (lane 4)." (PMID 24223835, 2013). "We could not detect significant changes in the level of GFAP in the hippocampus or frontal brain cortex either under the influence of insulin administration or under the influence of autophagy and apoptosis inhibitor administration in rats with brain ischemia and reperfusion." (PMID 39057034, 2024). "Thus, the neuroprotective effects of insulin against cerebral ischemia may be to boost the IRS1/Akt-mediated neurotrophic activity." (PMID 32492962, 2020). "Using an animal model of global brain ischemia, we found a ∼50% decrease in neuronal death in the CA1 hippocampal region with post-ischemic insulin administration." (PMID 24223835, 2013). "Indeed, insulin and insulin-like growth factor 1 (IGF-1) have been shown to play a key role in the CNS by regulating neuronal growth and plasticity with multiple effects in the brain, including neuroprotection in cerebral ischemia and stroke patients." (PMID 39062570, 2024). "Insulin administered intranasally activated the Akt-kinase (activating the mTORC1 complex, which inhibits autophagy) and inhibited the AMP-activated protein kinase (which activates autophagy) in the hippocampus and frontal cortex of rats with brain ischemia and reperfusion." (PMID 39057034, 2024).
hepatitis C (27 papers, 2010 to 2025). "Although this study had considered hepatitis B, hepatitis C, and alcohol consumption to be confounding factors, multivariate analysis was not performed to elucidate the independent association between insulin use and the HCC risk." (PMID 31200528, 2019). "The main aim was to elucidate the direct effect of hepatitis C virus (HCV) infection on insulin signaling both in vitro analyzing gene expression and protein abundance." (PMID 23133528, 2012). "Controls had a similar mean age to those with hepatitis C, but were more insulin resistant, obese and contained a lower percentage of males." (PMID 20862263, 2010). "Proinflammatory cytokine, hepatitis C virus infection or retinoic acid treatment was all reported to decrease IRS-1 protein level, resulting in suppression of insulin signal activity." (PMID 21991327, 2011). "The kinase(s) responsible for AMPK-αSer485 have not been extensively studied, although both insulin and hepatitis C have been reported to inhibit AMPK activation by mediating phosphorylation of this site by Akt/PKB." (PMID 22253816, 2012). "The obese HIV-infected subjects had a higher median age compared with the obese controls, and a higher smoking and hepatitis C prevalence, but did not significantly differ according to sex, race, BMI, FMI, or HOMA2 insulin sensitivity." (PMID 27175676, 2016).
influenza (27 papers, 2013 to 2025). An acute viral infection of the respiratory tract, occurring in isolated cases, in epidemics, or in pandemics; it is caused by serologically different strains of viruses (influenzaviruses) designated A, B, and C, has a 3-day incubation period, and usually lasts for 3 to 10 days. "Additionally, selective loss of insulin action attenuated the anti-inflammatory T cell response to influenza infection in murine immune cells." (PMID 33584268, 2020). "For example, higher outdoor temperature was associated with higher SPINK6 levels (maintaining skin homeostasis and restricting influenza activation), and shorter fasting time was associated with higher GIP levels (stimulating insulin secretion)." (PMID 41071435, 2025). "From this immunoreceptor sequencing, we identified TCRs specific for influenza and those reactive to insulin and its precursor, preproinsulin (PPI)." (PMID 38064552, 2023). "As an alternative to the conventional needles, hollow MNs have been used for influenza vaccine delivery and insulin delivery for diabetic patients." (PMID 33228098, 2020). "Taken together these data are consistent with recently published work that suggests alterations in glucose tolerance and insulin sensitivity in mice acutely infected with mCMV and influenza infection of mice being fed a high fat diet." (PMID 31220189, 2019). "After 12 days, we analysed culture supernatants for the presence of anti-influenza, anti-insulin, and anti-IL-2 IgG antibodies." (PMID 27708334, 2016). "If both insulin signaling and fatty acid oxidation are inhibited during influenza, it might result in suppression of the TCA cycle due to reduced substrate supply." (PMID 32616893, 2020). "At admission, patients displayed elevated HbA1c values (66 mmol/mol), a high prevalence of co-morbidities (88%), lipodystrophies due to monolocal insulin injections (42%), a low rate of influenza (16%) and pneumococcal (7%) immunization, and underuse of lipid-lowering drugs (-38%)." (PMID 29529063, 2018). "Therefore, it would be interesting to investigate influenza severity in a model in which obese mice have normalized insulin sensitivity and glucose tolerance." (PMID 24844920, 2014). "To examine this hypothesis, we investigated metabolic changes by determining the serum levels of metabolites, insulin sensitivity in the liver, glucose availability, and hepatic gene expressions in the early stages of symptom onset as well as the lethal phase of influenza in a mouse model." (PMID 32616893, 2020).
multiple myeloma (27 papers, 2011 to 2026). "In this study, we investigate the association between insulin signalling-induced IFITM1 expression and multiple myeloma (MM) aggressiveness." (PMID 42286874, 2026). "BM adipocytes secrete several adipokines and growth factors (e.g., MCP-1, SDF-1α, leptin, TNFα, insulin, resistin) which recruit myeloma cells and promote myeloma growth and protection from chemotherapy." (PMID 34067236, 2021). "Myeloma cells have been shown to possess functional insulin and IGF1 receptors." (PMID 35844707, 2021). "The patient had findings in the marrow compatible with myeloma and an IgG-lambda monoclonal immunoglobulin in the serum that was shown by insulin affinity chromatography, elution, and immunoelectrophoresis of the eluate to have bound insulin, specifically." (PMID 26241232, 2015). "Metformin reduces insulin and IGF1 production, increases insulin sensitivity and is thought to reduce the progression of monoclonal gammopathy of undetermined significance (MGUS) relative to multiple myeloma." (PMID 36830619, 2023). "Within the growth signalling network of the myeloma microenvironment, IL-6, IGF-1 and insulin play a prominent role." (PMID 25887188, 2015). "In this study we identified IGFBP7, a secreted factor with BMP antagonistic activity, and binding sites for IGF-1, insulin, VEGFA and activin A as a potential novel player in the pathogenesis of MM, including myeloma bone disease." (PMID 25887188, 2015). "For example, FNDC3A can bind FAM46C to inhibit multiple myeloma progression by regulating autophagy, and FNDC5 regulates the conversion of white fat to brown fat and improves insulin resistance by regulating the macrophage polarization, thereby reducing the validation response of adipose tissue." (PMID 36056336, 2022). "Future studies investigating connections between the insulin/IGF-1/AS160_v2/GLUT4 axis and FDG-PET positivity in myeloma patients are warranted and could provide rationale for therapeutically targeting this pathway in MM patients with advanced disease." (PMID 24280290, 2013). "Since insulin and IGF-1 are important myeloma growth factors there may exist a selective pressure in MM to upregulate genes that couple insulin/IGF-1 signaling to metabolic effectors that promote aerobic glycolysis." (PMID 24280290, 2013). "Similarly, growth of multiple myeloma cells treated with PPP could not be restored by insulin." (PMID 28793874, 2017). "The inhibitory effect on myeloma proliferation appears to be not only AMPK-independent, but must be independent of metformin's insulin-sensitizing and anti-hyperglycemic effects since they were observed in cell-based assays." (PMID 25605012, 2015). "The inhibitory effect of metformin on myeloma proliferation appears to be not only AMPK-independent, but must be independent of metformin's insulin-sensitizing and anti-hyperglycemic effects since these effects were observed in cell-based assays." (PMID 25605012, 2015).
psychosis (27 papers, 2016 to 2025). "Another study demonstrated that FEP patients have significantly higher levels of prolactin, fasting glucose, glycosylated hemoglobin and insulin resistance compared to individuals at clinical high risk of psychosis." (PMID 32547431, 2020). "Furthermore, insulin signaling disturbance in the brain is associated with impaired neurotransmitter signaling in preclinical models of psychosis." (PMID 40606939, 2025). "Therefore, the aim of this study is to evaluate the effect of a nursing intervention based on the carbohydrate–insulin model on weight loss and the management of MetS risk in people with recent onset psychosis." (PMID 39852625, 2024). "Disrupted insulin sensitivity could be a shared risk factor for comorbid cardiometabolic disorders and psychosis." (PMID 33439216, 2021). "Interestingly, this is paralleled by findings, indicating that perinatal stress is related to increased levels of insulin in a population with high risk of psychosis, and that childhood trauma is linked to increased insulin levels in patients with first episode psychosis." (PMID 33978833, 2021). "Post-hoc comparisons demonstrated significantly higher levels of insulin in patients with psychosis and a positive history of ACEs compared to other subgroups of participants." (PMID 33255883, 2020). "Their results showed that, at the time of the onset of psychosis, patients have a slight increase in fasting glucose, usually in the normal range, despite a small increase in IR, by secreting additional insulin." (PMID 32848941, 2020). "In summary, this study provides additional evidence of impaired adipoinsular axis, in terms of low leptin and high insulin levels, in early psychosis." (PMID 32547431, 2020). "Another case-control of drug-naïve, first-episode patients with psychosis showed higher insulin and C-peptide levels and lower HDL levels compared to the age- and BMI-matched controls." (PMID 28804444, 2017). "Recent studies found that the disruption of glucose-insulin homeostasis may presage psychosis, and that insulin resistance is related to pre-psychotic symptoms in young individuals before the onset of clinical psychosis." (PMID 38414502, 2024). "Peripheral biomarkers (e.g., insulin levels, metabolite levels in blood and urine) have been shown to be linked to treatment response in psychosis, but have not been consistent among studies." (PMID 32961543, 2021). "The authors found that at the time of first clinical contact for psychosis, patients have a slight increase in fasting glucose, which most of them maintain in the normal range, despite a small increase in IR, by secreting additional insulin." (PMID 30068291, 2018). "Interestingly, even in the first episode of psychosis, before initiation of antipsychotic drugs, affected subjects experience impaired appetite regulation in terms of significantly elevated insulin and decreased leptin levels, possibly correlating with negative emotional feelings." (PMID 36979648, 2023). "Previous studies have shown that insulin signaling, and glucose homeostasis are dysregulated in first-episode psychosis independent of antipsychotic treatment." (PMID 39085221, 2024). "Likewise some studies showed that antipsychotic naive patients with first episode psychosis (FEP) had increased prevalence of impaired glucose tolerance and were more insulin resistant than their healthy comparison subjects." (PMID 30068291, 2018).
bipolar disorder (26 papers, 2010 to 2026). A disorder of the brain that causes unusual shifts in mood, energy, activity levels and the ability to carry out day-to-day tasks. "Disrupted sleep, a core symptom of bipolar disorder, activates the sympathetic nervous system activation, reduces insulin secretion, and increases insulin resistance, which collectively result in elevated plasma free fatty acid levels." (PMID 40226688, 2024). "We have proposed that these metabolic features of bipolar disorder have a common root in dysfunction of insulin-signaling mechanisms, resulting in alternating states of glucose hypometabolism and hypermetabolism in the brain." (PMID 38273108, 2024). "Adjunctive intranasal insulin administration significantly improved a single measure of executive function in bipolar disorder." (PMID 34108878, 2021). "The odds for persons receiving insulin in monotherapy to also receive treatment for bipolar disorder was 1.7 (CI 95%: 1.5, 2.0) times higher than in the general population." (PMID 23186328, 2012). "In bipolar disorder, a less acute but chronic form of disruption of energy production may occur due to impaired insulin signaling, dysregulation of glucose metabolism and resultant mitochondrial dysfunction." (PMID 38273108, 2024). "It is suggested that developments in assessing neuronal insulin signaling using extracellular vesicles would allow for this hypothesis to be tested in bipolar disorder patients." (PMID 36038539, 2022). "In this paper, we propose that lithium may exert its therapeutic effect in bipolar disorder by acting on insulin signaling pathways." (PMID 36038539, 2022). "Impaired neuronal insulin signaling may represent a specific form of bipolar disorder amenable to treatment with insulin-sensitizing medications, and such tests could identify those who are likely to respond." (PMID 36038539, 2022). "An RCT among euthymic patients with bipolar disorder documented that individuals treated with intranasal insulin exhibited significant improvements in one measure of executive function (in the absence of improvement across other cognitive domains) compared with a placebo group." (PMID 26801406, 2016). "The inability of insulin to suppress GSK3 as observed in the strong lithium responders may serve as an indication of a unique form of lithium-responsive metabolic dysfunction in bipolar disorder patients." (PMID 36038539, 2022). "Whereas quetiapine affects bipolar depression via the MAPK and PI3K/AKT insulin signaling pathways, it affects bipolar mania through the neuroactive ligand‐receptor interaction signaling pathway." (PMID 40202273, 2025). "Some recent studies indicated that depressive symptoms in bipolar disorder and MDD can be improved by some antihyperglycemic agents through insulin sensitization." (PMID 38398483, 2024). "We found that the low dosage insulin or Li concentration used for patients with bipolar disorder did not affect fasting blood glucose levels in T1DM mice." (PMID 33660027, 2021). "The present pilot study tested the hypothesis that improvement of IR with the addition of an insulin-sensitizing agent would improve mood in nondiabetic patients with unipolar or bipolar depression, who had surrogate blood markers suggestive of IR." (PMID 20191245, 2010).